RAMP2 (receptor activity modifying protein 2)
Diseases named in the same sentence as RAMP2 in open-access papers (continued):
Sharing a sentence is not in itself a finding about the gene and the disease.
tumor (22 papers, 2014 to 2025). "PPI network analysis identified SELL, CD79B, and RAMP2 as hub genes, all significantly linked to survival and differentially expressed across tumor grades/stages." (PMID 40547199, 2025). "Subsequently, ADM2 and RAMP2 were identified as “tumor progression-associated genes” (TPAGs), as multiple experimental approaches revealed significant alterations in their expression during DCIS progression." (PMID 41150812, 2025). "In clinical samples of renal cell carcinoma, RAMP3 has shown to be predominantly expressed in inflammatory cells associated with the tumor whereas RAMP2 was mainly localized in the malignant cells." (PMID 33489885, 2020). "To investigate the functional roles of SELL, RAMP2, and CD79B in GC progression, we performed siRNA-mediated knockdown of these genes in GC cell lines and assessed their impacts on tumor-associated pathways via qPCR." (PMID 40547199, 2025). "SELL (a regulator of lymphocyte homing), RAMP2 (implicated in vascular remodeling), and CD79B (a B cell receptor component) exhibited tumor-specific upregulation and functional roles in GC proliferation, as validated by siRNA knockdown." (PMID 40547199, 2025). "Substantiating this premise, EC4 subclass analysis identified conserved functional modules including ECM remodeling effectors (HSPG2,MGP,POSTN) and tumor niche-modifying factors (RAMP2,ACKR1,CD74)." (PMID 41394809, 2025). "AM, CLR, and RAMP2/3 are present in ovarian cancer, and a high AM level has been related to the tumor stage." (PMID 36980580, 2023). "RAMP3 deficiency cancer-associated fibroblasts inhibited cell proliferation/migration and metastasis, and the activation of RAMP2 in RAMP3−/− mice blocked tumor growth and metastasis." (PMID 36980580, 2023). "AM, CLR, RAMP2, and RAMP3 have been reported in renal cancer, and a high level of CLR has been associated with a high tumor grade." (PMID 36980580, 2023). "RAMP2+ tumor endothelial cells (TECs) and PROX1+ lymphatic endothelial cells (LECs), were reduced in the PD-1+SMI group and highly expressed VEGF-associated receptor gene KDR (VEGFR1) and FLT1 (VEGFR2) compared with other endothelial subclusters." (PMID 37430270, 2023). "Subsequent immunofluorescence double-labelling experiments performed on various CALCRL-positive tumour specimens revealed that RAMP2 expression was predominant, with slightly lower expression of RAMP1." (PMID 36835377, 2023). "By contrast, tumor cell adhesion to vascular endothelial cells and metastasis to distant organs were suppressed in mice overexpressing RAMP2, which improved their survival rates, indicating that activation of the AM-RAMP2 system suppresses cancer metastasis." (PMID 35625516, 2022). "Using the EC-specific inducible deletion of Ramp2 KO mice (R2cKO, hereafter), the role of the vascular AM-RAMP2 system in both tumor angiogenesis and metastasis was examined." (PMID 35130955, 2022). "To evaluate the potential role of GC tumor-derived ADM in the degranulation of mast cells which expressed RAMP2 (specific subunit of ADM receptor 1 heterodimer) within tumors, we added ADMR antagonist AMA into TTCS/mast cell co-culture system." (PMID 30305610, 2018). "In renal tumours, for instance, RAMP2 was expressed in the tumour cells themselves, while RAMP3 elevation was found in inflammatory cells associated with the tumour, highlighting the importance of the interaction of the tumour with the microenvironment." (PMID 25475159, 2014). "Furthermore, the inducible deletion of pulmonary EC-specific Adrenomedullin (AM)-RAMP2 signaling results in increased permeability of tumor vessels, enhancing tumor metastasis." (PMID 40650130, 2025). "In vitro experiments further substantiate these findings, as ADM knockout inhibits proliferation, migration, and invasion of OSCC cells, reduces mRNA levels of MMP2, and induces compensatory upregulation of RAMP2, therefore suppressing tumor cell migration and invasion." (PMID 38256104, 2024).
tumor (continued). "Microvessel loss in the tumors treated with αAMRs may indicate that stimulation of the CLR/RAMP2/RAMP3-expressing tumor vasculature by AM is a survival mechanism rooted in the proliferation of tumor endothelia." (PMID 36497391, 2022). "In this sense, although its deficiency affects tumor vasculature and growth, RAMP2 does not appear to be a logical candidate for targeting given its role in preventing metastasis." (PMID 33489885, 2020). "In contrast to our data, it has been reported that an endothelium-specific knock-out of RAMP2, which together with CALCRL forms the adrenomedullin receptor, affects both retinal angiogenesis and tumor angiogenesis." (PMID 36374225, 2023). "AM impacts angiogenesis and tumor growth and binds to calcitonin receptor-like receptor/receptor activity-modifying protein 2 or 3 (CLR/RAMP2; CLR/RAMP3)." (PMID 36497391, 2022). "It is noteworthy to mention that, in some tumours, RAMP3 is expressed alongside RAMP2 while in others only RAMP2 is present." (PMID 25475159, 2014). "Tissue microarray analysis of human colorectal tumours revealed a clear increase of AM, CLR, RAMP2, and RAMP3 staining in lymph nodes and distant metastasis when compared with primary tumours." (PMID 25475159, 2014). "In contrast,EC5 and EC6 subclasses exhibited conserved pro-angiogenic signatures encompassing established vascular morphogenesis regulators (CD34,AQP1) and emerging angiocrine signaling components (RAMP2/3,CRIP2,PCDH17),consistent with previous reports on tumor neovascularization dynamics." (PMID 41394809, 2025). "A total of 3842 endothelial cells from seven tumor samples and one paracancerous tissue were obtained from the GEO database, based on the marker genes VWF, CDH5, RAMP2 and CLDN5,26, 27 of which 3724 and 118 cells were derived from cancer tissues and paracancerous tissue, respectively." (PMID 37726969, 2023). "In this model, selective activation of RAMP2 and inhibition of RAMP3 could suppress tumor metastasis." (PMID 36980580, 2023). "Furthermore, the levels of the AM receptors RAMP1, RAMP2, RAMP3, and CRLR were also elevated as compared to their adjacent non-tumor gastric tissues by 60%, 61%, 58%, and 62%, respectively." (PMID 29179449, 2017). "In contrast, but consistent with public databases, all primary tumours had detectable message for CALCRL and all RAMPs with one cell line losing detectable CALCRL expression along with 3 xenografts, one xenograft losing RAMP2 and 7 cell lines and 5 xenografts having no detectable RAMP3." (PMID 30777055, 2019).
cancer (11 papers, 2020 to 2025). A tumor composed of atypical neoplastic, often pleomorphic cells that invade other tissues. "The observation means that RAMP2 activation and RAMP3 inhibition can suppress metastasis, and that deficiency of the AM/RAMP3 system inhibited metastasis via the modification of cancer-associated fibroblasts." (PMID 36980580, 2023). "Transplantation of cancer cells into drug-inducible vascular endothelial cell-specific RAMP2 knockout mice resulted in enhanced metastasis to distant organs, whereas metastasis was suppressed in RAMP3-/- mice." (PMID 35625516, 2022). "RAMP2 suppresses cancer metastasis by maintaining vascular homeostasis and inhibiting vascular inflammation and pre-metastatic niche formation, while RAMP3 promotes cancer metastasis via malignant transformation of cancer-associated fibroblasts." (PMID 35625516, 2022). "We investigated the association between the AM-RAMP2 system in blood vessels and cancer growth and metastasis, using DI-E-RAMP2-/- mice to deplete RAMP2 in the vascular endothelial cells of adults." (PMID 35625516, 2022). "Additionally, genes such as EEF1A2 (protein synthesis and cancer cell survival), RAMP2 (cardiovascular homeostasis), PLAGL1 (cell growth suppression and differentiation activation), and STRIP2 (stem cell differentiation and cell morphology regulation) were also suppressed." (PMID 40427555, 2025). "Thus, RAMP2.AS1/miR-30b-5p/ESR1 and RAMP2.AS1/miR-30b-5p/FOXA1 axes might be involved in the pathogenesis of this kind of cancer." (PMID 34094972, 2021). "Ultimately, we conducted a thorough analysis of the expression patterns of these genes across various cancer types and uncovered that, in GC, the expression levels of SELL and RAMP2 are significantly elevated compared to normal tissue." (PMID 40547199, 2025). "In addition, fibroblasts (n = 1 068) were identified by COL1A1 and FAP, endothelial cells (n = 2 561) were positive for RAMP2 and CLDN5 expression, smooth muscle cells (n = 1 100) were defined by TAGLN and CNN1, and epithelial/cancer cells (n = 319) were labeled by KRT14 and KRT17." (PMID 40360503, 2025).
bacterial infection (1 paper, 2016). "In view of the presently demonstrated LPS-induced up-regulation of AM, IMD, and RAMP2 in NR8383 cells, this signaling pathway may function in a similar manner as an auto-/paracrine inhibitory feedback mechanism in bacterial infection." (PMID 27737007, 2016).
heart diseases (1 paper, 2022). "How RAMP2 and RAMP3 are related to the pathogenesis of these various heart diseases requires further investigation." (PMID 35625516, 2022).
RAMP2 also shares sentences with these, for which no sentence is quoted: lung carcinoma (2 papers); autoimmune uveitis (1); cardiac hypertrophy (1); cardiovascular diseases (1); chondrosarcoma (1); colitis (1); colon cancer (1); ductal carcinoma in situ (1); glioma (1); infection (1); kidney disease (1); leukaemia (1); lung adenocarcinoma (1); lymphedema (1); mesothelioma (1); migraine with aura (1); Nephropathy (1); osteoarthritis (1); periodontitis (1); pilocytic astrocytoma (1); preeclampsia (1); Renal Dysfunction (1).